EGFR (epidermal growth factor receptor)
Diseases named in the same sentence as EGFR in open-access papers (continued):
Sharing a sentence is not in itself a finding about the gene and the disease.
cancer (continued). "The anti-EGFR sdAbs can be fused to a toxic molecule to form an antibody-drug conjugate (ADC) to strengthen cancer cell killing." (PMID 33023595, 2020). "Epidermal growth factor receptor (EGFR) plays a substantial role in the invasion and proliferation of cancer cells and modifies angiogenesis and apoptosis." (PMID 33291312, 2020). "As upstream of mTOR and MAPKs, epidermal growth factor receptor (EGFR) expression is inhibited by miRNA-7 to induce autophagic cell death in human cancer cells." (PMID 33239065, 2020). "Oncosomal molecular cotransfer of oncoproteins such as mutant EGFR and amplified HSPs can thus promote oncogenesis and resistance to stress and therapy in cancer cells themselves and in the recipient cells at the local and distant milieu." (PMID 32150875, 2020). "A relationship between the EGFR signaling pathway expression in skin and the use of targeted cancer therapies has been previously demonstrated." (PMID 33015988, 2020). "In particular, diet-modulated miRNAs were able to target and interfere with several genes mainly involved in cancer signal transduction pathways (e.g., EGFR, RAC1, PLCG1, FOS, NRAS, SOS2, etc.)." (PMID 32911851, 2020). "It appears that in cutaneous squamous cell carcinoma, EGFR activates NF-κB signaling pathway to elevate the progression and malignancy of cancer cells." (PMID 32503307, 2020). "ECM proteins Laminin-5, Tenascin-C, and Decorin bind EGFR to regulate its activation and function in cancers." (PMID 32719793, 2020). "PIC–Nal not only improved PIT efficacy against EGFR-overexpressing cancer cells, but provided us an opportunity to co-deliver irinotecan chemotherapy to further enhance treatment outcomes." (PMID 31898555, 2020). "The suppression of cancer cell metastasis thru the down‐regulation of EGFR‐activated MMP‐9 has been presented." (PMID 32180962, 2020). "Given the EGFR signalling pathway is commonly hyperactivated in human cancers, and the positive correlation between EGFR and NKG2DL expression in human carcinomas." (PMID 33352921, 2020). "The effect of sERr on major proto-oncogenes, such as c-MET and EGFR, invokes a mechanism for cancer treatment." (PMID 32161259, 2020). "Cetuximab, an antibody targeting EGFR, is a well-known and widely-used anti-cancer monotherapy in clinical practice." (PMID 32117774, 2020). "We assessed the anticancer activity of DPBA (5 μM) on a panel of cancer cell lines in order to validate the association between the anticancer activity of DPBA and the EGFR levels." (PMID 33033232, 2020). "Five human anti-EGFR sdAbs were identified and tested for their effect on the three different cancer cell lines." (PMID 33023595, 2020). "Activation of EGFR triggers various downstream signaling pathways that mediate cellular proliferation or metabolism, playing vital roles in cancer initiation and progression." (PMID 32296018, 2020). "Dysregulated epidermal growth factor receptor (EGFR) is an oncogenic driver of many human cancers, promoting aberrant cell proliferation, migration, and survival." (PMID 32050662, 2020). "In some studies, the EGF/EGFR signaling pathway has been known to contribute significantly to the formation and maintenance of CSCs in various cancer." (PMID 32376896, 2020). "The cellular experiments showed that HD-SB significantly induced cancer cell apoptosis, decreased p-EGFR, HSP90 and bcl-2 expressions, and increased PPARγ, bax, cleaved caspase 3, cleaved PARP, p-AKT, and p-PI3K expressions compared with HD or SB treatment." (PMID 32265701, 2020). "Of note, USP18 has been demonstrated to be a positive regulator of epidermal growth factor receptor (EGFR) by inactivating microRNA-7 (miR–7) that is known to reduce the expression of EGFR mRNA in cancer cells." (PMID 32957626, 2020). "EGFR signaling is highly activated in cancer;therefore, we sought to determine the dynamics of EGFR activation and FOXO4 regulation." (PMID 33101846, 2020).
cancer (continued). "Since then, several other small molecule EGFR inhibitors have been developed and used to treat a variety of cancers, including erlotinib, afatinib, lapatinib, and dacomitinib." (PMID 33112928, 2020). "Recently, a novel strategy to treat cancer cells expressing a higher level of the EGFR used an epidermal growth factor-gold nanoparticle (EGF-GNP) conjugate complex." (PMID 31963462, 2020). "EGFR has long been a popular target in cancer therapy, as the over-expression and/or over-activation of EGFR contributes to the malignant growth, metastasis and poor prognosis of various cancers." (PMID 32745124, 2020). "EGFR activation induces cell proliferation, neoformation of blood vessels, survival, and metastasis of the cancer cells." (PMID 32537431, 2020). "As mentioned, AXL has been previously shown to mediate resistance to various anti-cancer agents, including EGFR, HER2 and PI3K-targeted therapies." (PMID 33059733, 2020). "This has implications in understanding the response to EGFR inhibitors in cancer treatment where resistance and inflammatory skin lesions are two major causes for treatment cessation." (PMID 32054454, 2020). "This construct has demonstrated the ability to image high EGFR expressing cancer cell lines and human tissue samples." (PMID 33121022, 2020). "Recent studies have demonstrated that EGFR-TKIs also have a certain inhibitory effect on EGFR-WT cancer cells." (PMID 33276757, 2020). "The EGFR signaling pathway has been reported to be one of the mechanisms by which EMT-like features are induced in various cancers." (PMID 32977534, 2020). "The output of this screen would, therefore, be useful to all researchers who study negative regulators of growth during development and cancer in the context of activated EGFR and/or Yki." (PMID 32737065, 2020). "For a subset of the 1,316 patients tested for EGFR mutations, NGS tests including other cancer mutation hotspots were performed." (PMID 32714871, 2020). "EGF is one of the growth factors capable of binding to EGFR, and plays a major role in cell growth, migration, invasion, and metastasis, and is highly presented in many human cancer types." (PMID 32376896, 2020). "Approximately 90% and 75% of cancer patients receiving EGFR inhibitors (EGFRI) Mabs and TKIs, respectively, develop a papulopustular eruption within the first 2–3 weeks after the start of therapy, and the toxicity is often dose-dependent." (PMID 32642992, 2020). "Patients with phosphorylated EGFR-dependent cancer cell proliferation and metastasis are well-suited for therapy with EGFR TKIs." (PMID 32756527, 2020). "Due to its complex role in the progression of cancer, EGFR is an important target for cancer therapy." (PMID 33158043, 2020). "The expression of EGFR was first identified in 2008 at protein and mRNA level in sEVs derived from cultured EGFR-positive cancer cell lines and clinical samples." (PMID 33228060, 2020). "Additional mechanisms underlying EGFR-induced progression of CC involve the direct activation of c-Met, the tyrosine kinase receptor for HGF which contributes to the malignancies of cancer." (PMID 32708604, 2020). "Crosstalk between c-MET and epidermal growth factor receptor (EGFR) is involved in the progression of many types of cancers." (PMID 33217986, 2020). "β-elemene as an antitumor agent diminishes the migration and invasion of cancer cells by the inhibition of EGFR signaling." (PMID 32380783, 2020). "Nbs as targets for cancer have been developed against EGFR, HER2, VEGFR2, and continue to be developed for overcoming the immune suppression of the TME and targeting adaptive and innate immune checkpoints amongst other targets." (PMID 32937961, 2020). "This is important in light of the attempts to assess the feasibility of using both the levels of GOLPH3 and the inhibition of EGFR glycosylation as tools to downregulate EGFR signaling and sensitize cancer cells to anticancer therapies." (PMID 33238647, 2020).
cancer (continued). "In another study, 111In-labeled polymeric nanoparticles incorporating a ruthenium-based radiosensitizer were reported to achieve combinational and targeted therapeutic effects in cancer cells that overexpress EGFR (Human Epidermal Growth Factor Receptor)." (PMID 33118416, 2020). "Our findings suggest that EGF conjugation increases the uptake level and decreases the cell proliferative effect of TiO2 PEG NPs by EGFR-overexpressing cancer cells." (PMID 33003324, 2020). "Gefitinib is the first generation of EGFR-TKI to target EGFR-19del and EGFR-L858R mutation, but it has been less effective in CRC management than in other types of cancer." (PMID 32756527, 2020). "Anti-EGFR antibodies—e.g., cetuximab, panitumumab, necitumumab, and nimotuzumab—have been used for treating EGFR-positive cancers." (PMID 33233524, 2020). "While D3 significantly improves efficacy of EGFR TKIs, it also augments the efficacy of other drugs across a wide range of cancer types." (PMID 32066763, 2020). "Cancer cell sensitivity to DPBA was positively correlated with the EGFR messenger RNA (mRNA) and protein levels." (PMID 33033232, 2020). "We found a correlation between PODXL and EGFR in these cancers, and a synergistic adverse effect on survival." (PMID 32587323, 2020). "Given its role in diverse cellular processes and its activation in a wide array of cancers, EGFR stands out as a prime therapeutic target." (PMID 33112928, 2020). "These stress neurotransmitters activate β-adrenergic receptors to stimulate the release of EGF, leading to activated EGFR signaling cascade and the development and progression of numerous cancers." (PMID 32957649, 2020). "This novel format of β-defensin, which induces mitochondrial-mediated apoptosis, is likely to play an active role in EGFR-targeting cancer therapy." (PMID 33114695, 2020). "Nowadays, cancer patients are routinely treated with therapeutic agents such as erlotinib and gefitinib to suppress EGFR signaling or crizotinib and cabozantinib targeting MET." (PMID 32316583, 2020). "The presence of surface EGF allows EGF-PLGA@5Fu/PFC NPs to interact strongly with EGFR, which results in anchoring of these NPs to cancer cells that express high levels of EGFR." (PMID 32345258, 2020). "The human epidermal growth factor receptor (HER) family is composed of four different members that have been thoroughly investigated due to their important role in cancer progression." (PMID 33192518, 2020). "For the peptide B74–94, such a target can be represented by the epidermal growth factor receptor amplified in the triple-negative cancer cell line BT-20 and overexpressed in several types of cancer." (PMID 33375305, 2020). "It is known that EGFR protein expression is significantly different in the case of left- versus right-sided cancers." (PMID 32155907, 2020). "In previous studies, AKT pathway reactivation was reported to play an important role in cancer cell survival in response to EGFR TKI treatment." (PMID 32404161, 2020). "The epidermal growth factor receptor (EGFR) plays a critical role in cancer since it mediates proliferation by activation of Ras and STAT." (PMID 32719397, 2020). "The autophagic degradation of EGFR is often suppressed in cancer, and activation of this process indicates antitumour activity." (PMID 32732965, 2020). "Among the overlap target genes, epidermal growth factor receptor (EGFR) was selected because of its role in cancer development." (PMID 32685551, 2020). "We have reported that the domain order affects the function of a humanized bsDb targeting EGFR on cancer cells and CD3 on T cells (hEx3-Dbs)." (PMID 33255436, 2020).
cancer (continued). "EGFR is over expressed on the surface of cancer cells from several origins and is one of the most studied surface receptors for targeted cancer therapeutics." (PMID 32075165, 2020). "Mutations and truncations of its extracellular matrix leads to upregulation of EGFR in several cancers, including NSCLC." (PMID 33198090, 2020). "In cancer, Neu-1 inhibition by oseltamivir changes epidermal growth factor receptor (EGFR)-mediated signaling and shift cadherin expression that reduces metastatic potential and chemoresistance in various malignant cells." (PMID 32575400, 2020). "For example, the epidermal growth factor receptor (EGFR) was overexpressed in many cancers, and it was leading to overexpression and constitutive activation of EFGR tyrosine kinase activity." (PMID 31936239, 2020). "In this study we found that EGFR inhibition treatment induced complement activation on the cell surface of cancer cells." (PMID 32054454, 2020). "Many oncogene-driven cancers such as those with alterations in EGFR, ALK, ROS1, and BRAF are treated with targeted therapies against the cognate oncoprotein." (PMID 32822576, 2020). "Clinical application showed that the anti-EGFR antibodies were effective for cancer therapy, and EGFR was an important anti-cancer target." (PMID 33023595, 2020). "Of these, 29 are associated with activation of EGFR and/or FGFR1 gene products in varying types of cancer (FDR qvalue = 4.68e− 15 and 3.74e− 15, MutsigDB)." (PMID 32209086, 2020). "HER2 overexpression found in other cancers, like esophageal adenocarcinoma, was shown to also have an inhibitory effect on autophagy, and treatment with the dual EGFR/HER2 inhibitor Lapatinib also induced autophagic flux in vitro." (PMID 33287140, 2020). "The mechanism of EGFR activation and the role of EGFR signaling in cancer progression have been well studied." (PMID 31991585, 2020). "All these data suggest the implication of Cbl ubiquitin-ligases in EMT by EGFR modulation in several cancer types." (PMID 33114139, 2020). "Numerous studies indicated that KRAS mutations serve as prognostic and predictive biomarkers in multiple types of cancer, as it can provide information for patients’ survival outcomes and suggestions on the use of EGFR-inhibitors." (PMID 33254149, 2020). "EGFR tyrosine kinase inhibitors are currently available as chemotherapeutic agents, which have shown to improve survival in patients with EGFR-mutant cancer." (PMID 31900168, 2020). "Our findings support the idea of evaluating the EGFR status in GSCs when choosing therapeutic strategies aimed at eliminating cancer stem cells." (PMID 32788653, 2020). "RM‐NPC patients who received first‐line chemotherapy plus an anti‐EGFR antibody were recruited from Sun Yat‐Sen University Cancer Center between July 2007 and November 2017." (PMID 31955525, 2020). "Cell surface oncoproteins, such as CD326/EpCAM, EGFR, and programmed cell death-ligand 1 (PD-L1), are often released from cancer cells by two mechanisms including secretion in exosomes and protein shedding by proteinases." (PMID 32150875, 2020). "This review will focus on hypoxia, cancer stem cells, and specific signaling pathways of EGFR, NFκB, and Hedgehog as well as DNA damage signaling involving PARP, as mechanisms of radioresistance for which pharmacological targets have been identified." (PMID 32117774, 2020). "Small molecule tyrosine kinase inhibitors, such as gefitinib, afatinib, erlotinib and osimertinib and anti-EGFR monoclonal antibodies including cetuximab and panitumumab, prolong survival in cancer patients." (PMID 32706027, 2020).
cancer (continued). "Some mAbs, such as cetuximab and panitumumab, target the epidermal growth factor receptor (EGFR) which is overexpressed in a number of cancers." (PMID 33013848, 2020). "Inhibition of cancer cell metastasis by honokiol via EGFR‐ and vascular endothelial growth factor (VEGF)‐mediated signaling pathway has been noted in xenograft tumor model." (PMID 32180962, 2020). "This displayed a specific novel anti-cancer gene therapy strategy which combines EGFR inhibition as well as CASP3 induced apoptosis." (PMID 33381459, 2020). "The effectiveness of EGFR TKIs used in targeted cancer treatment therapy is very often restricted owing to the development of acquired resistance, which is often triggered by fresh mutations in targeted kinases." (PMID 32666476, 2020). "A panel of four pan-cancer markers (EGFR, EPCAM, HER2, and MUC1) and three putative PC markers (GPC1, WNT2, and GRP94) were investigated individually and together in plasma-derived exosomes." (PMID 33297544, 2020). "KEGG analysis suggested that the pathways notably enriched in the differentially expressed genes were “galactose metabolism,” “EGFR tyrosine kinase inhibitor resistance,” “pathways in cancer,” and “PI3K-Akt pathway”." (PMID 33294057, 2020). "N-nitroso compounds give rise to excessive expression of cyclinE 1, cyclinD 1, transform growth factor α and epidermal growth factor receptor in esophageal tissues, thus enhance cancer progression." (PMID 32252671, 2020). "In many other types of cancers, the inhibition EGFR signaling was found to be an effective method to fight cancer; however, its amplification in GBM have failed so far." (PMID 33053907, 2020). "This provides the rationale for a sequential TRK inhibitor treatment approach in patients with TRK fusion cancer, similar to current practice in oncogene-addicted (e.g. EGFR, ALK) NSCLC." (PMID 32891793, 2020). "The enormous amount of related literature in the last 5 years prompted us to collect all these published data from screening against cancer cell lines, or protein targets like EGFR and structure activity relationship studies." (PMID 32752126, 2020). "The epidermal growth factor receptor (EGFR) pathway is one of the most dysregulated molecular pathways in human cancers." (PMID 32093124, 2020). "The epidermal growth factor receptor (EGFR), eliciting a ligand-dependent response in different cancer cell lines, is considered a master regulator of invadopodia." (PMID 33178698, 2020). "Principally, EGFR and HER2 appear mutated in several epithelial tumors and have been implicated in the development and progression of cancer." (PMID 32316671, 2020). "Over the past decade, WBP2 surfaced as a key node connecting key signaling pathways associated with ER/PR, EGFR, PI3K, Hippo, and Wnt in cancer." (PMID 32393834, 2020). "The combination of EGFR‐TKI with other agents induced a more potent inhibitory effect against cancer." (PMID 32248643, 2020). "Dysregulated EGFR signaling is well-known in leading to several cancers but there is now strong evidence for its importance in other pathologies that result in pain as well as in the underlying mechanisms of pain sensing and processing." (PMID 32547536, 2020). "The EGFR/HER2-RAS-RAF-MEK-ERK1/2 signaling pathway plays a key role in cancer development and progression." (PMID 32398965, 2020). "Hyperspectral imaging of post-surgical specimens of SCC stained with GNPs conjugated to EGFR antibodies revealed most of the histologically-proven cancer sites." (PMID 31963462, 2020). "Here, we used single-molecule super-resolution microscopy to simultaneously visualize single MET and epidermal growth factor receptor (EGFR) clusters in two cancer cell lines, HeLa and BT-20, in fixed and living cells." (PMID 32316583, 2020).